RPAIN (RPA interacting protein)
Description:
Mediates the import of RPA complex into the nucleus, possibly via some interaction with importin beta. Isoform 2 is sumoylated and mediates the localization of RPA complex into the PML body of the nucleus, thereby participating in RPA function in DNA metabolism.
Synonyms: hRIP; RIP; MGC4189
Tractability: PROTAC: UniProt records ubiquitination sites on it; ubiquitination databases record sites on it; its protein half-life has been measured.
Gene: Protein-coding gene on chromosome 17 (5,419,216 to 5,432,882, forward strand). Ensembl gene ENSG00000129197.
Subcellular location: Cytoplasm (Isoform 1); Nucleus; Nucleus, PML body (Isoform 2)
Subcellular location (Human Protein Atlas): Nucleoli fibrillar center; Nucleoplasm
Gene Ontology:
Molecular function: protein binding
Biological process: protein import into nucleus
Cellular component: nucleoplasm; nucleus; cytoplasm; PML body
Genetic constraint (gnomAD): Loss-of-function variants: 26 observed, 26.55 expected, observed/expected ratio (o/e) 0.98, 90% interval 0.72 to 1.36. The upper end of that interval is the gene's LOEUF score, 1.36, which puts it in group 5 of 6, group 1 being the genes least tolerant of losing a copy. Missense variants: 235 observed, 260.43 expected, observed/expected ratio (o/e) 0.9, 90% interval 0.81 to 1. Synonymous variants: 98 observed, 95.54 expected, observed/expected ratio (o/e) 1.03, 90% interval 0.87 to 1.21.
Homologues: Orthologues: chimpanzee RPAIN (97% identical), macaque RPAIN (93% identical), pig RPAIN (79% identical), guinea pig RPAIN (77% identical), rat Rpain (74% identical), mouse Rpain (72% identical), dog RPAIN (71% identical), rabbit RPAIN (58% identical), zebrafish rpain (41% identical), tropical clawed frog rpain (39% identical), Drosophila melanogaster Ripalpha (22% identical).
Diseases named in the same sentence as RPAIN in open-access papers:
RPAIN is named in the same sentence as 25 diseases in open-access papers, as found by Europe PMC text mining. Sharing a sentence is not in itself a finding about the gene and the disease. The quoted sentences say what the papers report.
influenza (2 papers, 2021). An acute viral infection of the respiratory tract, occurring in isolated cases, in epidemics, or in pandemics; it is caused by serologically different strains of viruses (influenzaviruses) designated A, B, and C, has a 3-day incubation period, and usually lasts for 3 to 10 days. "Several polymorphisms which have been known for the susceptibility to influenza infection include CD55, C1QBP, FCGR2A, IFITM3, TNF, RPAIN, LTA and KIR." (PMID 33766078, 2021).
pneumonia (2 papers, 2020 to 2021). An acute, acute and chronic, or chronic inflammation focally or diffusely affecting the lung parenchyma, caused by an infection in one or both of the lungs (by bacteria, viruses, fungi, or mycoplasma.). "In regards to rs8070740 and rs9856661 at RPAIN and unknown genes, respectively, it was suggested that these genes polymorphisms might impact the susceptibility to severe pneumonia in A/H1N1 infection." (PMID 33766078, 2021).
preeclampsia (2 papers, 2017 to 2025). Preeclampsia is a hypertensive disorder of pregnancy that is characterized by new-onset hypertension with proteinuria presenting after 20 weeks of gestation, and depending on mild or severe forms may initially present with severe headache, visual disturbances, and hyperreflexia. "Therefore, we proposed RPAIN as a novel lncRNA molecule, which might contribute to the development of PE (preeclampsia) and might compose a potential diagnostic and therapeutic target for this disease." (PMID 28032589, 2017). "In this study, we show that lncRNA RPAIN is upregulated in preeclampsia and functions in preeclampsia via the complement protein C1q." (PMID 28032589, 2017). "To investigate the potential role of RPAIN in the pathophysiology of PE, we first examined the expression level of RPAIN in 25 preeclampsia placenta tissues and 15 normal tissues using quantitative real-time PCR (qRT-PCR) (P < 0.05)." (PMID 28032589, 2017). "In this study, we aimed to investigate the possible role of lncRNA RPAIN in the pathophysiology of early onset preeclampsia and its function in trophoblast biology." (PMID 28032589, 2017). "The data indicated that RPAIN was upregulated in the early onset preeclampsia samples compared to the normal samples." (PMID 28032589, 2017). "In conclusion, these results suggest that C1q is a potential target of RPAIN in preeclampsia." (PMID 28032589, 2017). "Our results suggest that increased RPAIN levels may contribute to the development of preeclampsia through regulating trophoblast invasion and apoptosis via C1q." (PMID 28032589, 2017). "The present study suggests that the RPAIN/C1q pathway could represent a mechanism of pathogenesis in preeclampsia." (PMID 28032589, 2017). "In general, these results indicated that C1q is a functional target gene of RPAIN in preeclampsia." (PMID 28032589, 2017). "Therefore, we hypothesized that abnormal RPAIN in the placenta might play a significant role in the pathogenesis of preeclampsia; abnormal expression of RPAIN in preeclamptic placentas could exert an aberrant regulation effect on the invasion and apoptosis of trophoblasts via C1q." (PMID 28032589, 2017). "Previously, based on a lncRNA microarray analysis, we found that lncRNA RPAIN (transcript variant 13 of RPA interacting protein, a non-coding RNA, NR_027683.1) was overexpressed in preeclampsia placenta tissues." (PMID 28032589, 2017). "The high levels of expression of RPAIN in preeclampsia may affect the biological function such as proliferation, apoptosis, and invasion of placental trophoblast cells through C1QBP, which participates in the occurrence and development of preeclampsia." (PMID 40454173, 2025).
diabetes (1 paper, 2021). "The results showed that possessing the G allele in either rs3786054 or rs8070740 loci in C1QBP and RPAIN genes, respectively, increased the risk of H1N1 infection up to 3.3 folds, regardless of the patient’s age, BMI, diabetes, and hypercholesterolemia." (PMID 33766078, 2021).
lentivirus infection (1 paper, 2017). Virus diseases caused by the Lentivirus genus. "Thereafter, we generated a “rescue” assay to investigate the effect of RPAIN overexpression in the presence of C1q overexpression by lentivirus infection of C1q after stable infection of RPAIN in HTR-8/SVneo cells." (PMID 28032589, 2017).
RPAIN also shares sentences with these, for which no sentence is quoted: breast carcinoma (3 papers); cancer (3); infection (2); basal cell carcinoma (1); bladder cancer (1); brain cancer (1); cancer of female genital organs (1); cancer of male genital organs (1); gastric cancer (1); Globozoospermia (1); Hypercholesterolemia (1); influenza A H1N1 virus infection (1); liver cancer (1); lung carcinoma (1); melanoma (1); oesophageal cancer (1); ovarian carcinoma (1); prostate carcinoma (1); skin cancer (1); Tumor (1).